RNU6-644P (RNA, U6 small nuclear 644, pseudogene)
Gene: Small nuclear RNA gene on chromosome 5 (116,188,455 to 116,188,552, reverse strand). Ensembl gene ENSG00000212457.
Homologues: Orthologues: chimpanzee U6 (98% identical), macaque U6 (91% identical), dog U6 (83% identical), guinea pig U6 (80% identical), pig U6 (80% identical), rat U6 (80% identical), dog U6 (76% identical). Paralogues in human: RNU6-144P (85% identical), RNU6-21P (85% identical), RNU6-1270P (84% identical), RNU6-140P (84% identical), RNU6-211P (84% identical), RNU6-33P (84% identical), RNU6-455P (84% identical), RNU6-891P (84% identical), RNU6-949P (84% identical), RNU6-1 (83% identical), RNU6-1152P (83% identical), RNU6-116P (83% identical), and 1290 more.